IGF2BP3 (insulin like growth factor 2 mRNA binding protein 3)
Description:
RNA-binding factor that may recruit target transcripts to cytoplasmic protein-RNA complexes (mRNPs). This transcript 'caging' into mRNPs allows mRNA transport and transient storage. It also modulates the rate and location at which target transcripts encounter the translational apparatus and shields them from endonuclease attacks or microRNA-mediated degradation. Preferentially binds to N6-methyladenosine (m6A)-containing mRNAs and increases their stability. Binds to the 3'-UTR of CD44 mRNA and stabilizes it, hence promotes cell adhesion and invadopodia formation in cancer cells. Binds to beta-actin/ACTB and MYC transcripts. Increases MYC mRNA stability by binding to the coding region instability determinant (CRD) and binding is enhanced by m6A-modification of the CRD. Binds to the 5'-UTR of the insulin-like growth factor 2 (IGF2) mRNAs.
Synonyms: IMP-3; IMP3; KOC1; VICKZ3; CT98; KOC
Tractability: PROTAC: UniProt records ubiquitination sites on it; ubiquitination databases record sites on it; its protein half-life has been measured.
Gene: Protein-coding gene on chromosome 7 (23,310,209 to 23,470,491, reverse strand). Ensembl gene ENSG00000136231.
Subcellular location: Nucleus; Cytoplasm; Cytoplasm, P-body; Cytoplasm, Stress granule
Subcellular location (Human Protein Atlas): Cytosol
Pathways (Reactome):
Metabolism of RNA: Insulin-like Growth Factor-2 mRNA Binding Proteins (IGF2BPs/IMPs/VICKZs) bind RNA
Gene Ontology:
Molecular function: mRNA 3'-UTR binding; mRNA 5'-UTR binding; N6-methyladenosine-containing RNA reader activity; protein binding; RNA binding; translation regulator activity; nucleic acid binding
Biological process: CRD-mediated mRNA stabilization; anatomical structure morphogenesis; negative regulation of translation; nervous system development; regulation of cytokine production; translation
Cellular component: cytoplasm; cytoplasmic stress granule; cytosol; P-body; nucleus
Genetic constraint (gnomAD): Loss-of-function variants: 5 observed, 53.6 expected, observed/expected ratio (o/e) 0.0933, 90% interval 0.048 to 0.2. The upper end of that interval is the gene's LOEUF score, 0.2, which puts it in group 1 of 6, group 1 being the genes least tolerant of losing a copy. Missense variants: 467 observed, 627.94 expected, observed/expected ratio (o/e) 0.74, 90% interval 0.69 to 0.8. Synonymous variants: 217 observed, 229.4 expected, observed/expected ratio (o/e) 0.95, 90% interval 0.85 to 1.06.
Homologues: Orthologues: chimpanzee IGF2BP3 (100% identical), macaque IGF2BP3 (99% identical), dog IGF2BP3 (99% identical), rat Igf2bp3 (97% identical), mouse Igf2bp3 (97% identical), guinea pig IGF2BP3 (88% identical), rabbit IGF2BP3 (88% identical), pig IGF2BP3 (87% identical), tropical clawed frog igf2bp3 (77% identical), zebrafish igf2bp3 (77% identical), Drosophila melanogaster Imp (35% identical), Caenorhabditis elegans imph-1 (25% identical), and 6 more. Paralogues in human: IGF2BP1 (73% identical), IGF2BP2 (66% identical), KHSRP (19% identical), FUBP1 (18% identical), FUBP3 (17% identical), PCBP2 (16% identical), PCBP3 (16% identical), PCBP4 (16% identical), PCBP1 (16% identical), HNRNPK (15% identical), NOVA2 (13% identical), NOVA1 (12% identical).
Diseases named in the same sentence as IGF2BP3 in open-access papers:
IGF2BP3 is named in the same sentence as 219 diseases in open-access papers, as found by Europe PMC text mining. Sharing a sentence is not in itself a finding about the gene and the disease. The quoted sentences say what the papers report.
glioma (80 papers, 2015 to 2026). A benign or malignant brain and spinal cord tumor that arises from glial cells (astrocytes, oligodendrocytes, ependymal cells). "Co-culture of glioma cells with human microglia (HM) cells demonstrated that IGF2BP3-KD U87 and HS683 cells were more susceptible to phagocytosis by microglia." (PMID 38429265, 2024). "Increasing evidence suggests that IGF2BP3 is frequently overexpressed and associated with unfavorable prognosis in various cancer types, including glioma." (PMID 38429265, 2024). "The examination of 19 m6A RNA methylation modulators in gliomas highlighted IGF2BP3 as the most markedly altered gene associated with m6A RNA methylation." (PMID 38398118, 2024). "One particular RBP, IGF2BP3, has been linked with metabolic reprogramming in various diseases like gastric cancer, lung cancer, and glioma." (PMID 38760723, 2024). "IGF2BP3 (Insulin-like growth factor 2 mRNA binding protein 3) protein has been reported as an oncogene protein associated with glioma." (PMID 37407973, 2023). "Insulin-like growth factor 2 mRNA binding protein 3 (IGF2BP3) is a known oncogenic protein molecule associated with the malignant progression of gliomas." (PMID 36497204, 2022). "Though several studies have identified IGF2BP3 as a poor prognostic marker in glioma, the underlying mechanism remains unclear." (PMID 38429265, 2024). "In addition, IGF2BP3 was specifically highly expressed in glioma cells, enhancing its role as a diagnostic marker." (PMID 38053093, 2023). "Copy number variation and DNA methylation, but not somatic mutations, might contribute to the abnormal upregulation of IGF2BP3 in gliomas." (PMID 34721530, 2021). "Notably, we found that IGF2BP3 expression predicted a poor prognosis and was an independent risk factor for OS of patients with glioma." (PMID 34721530, 2021). "IGF2BP3 may be associated with malignant progression of IDH1-mutant gliomas and be a candidate therapeutic target." (PMID 30760837, 2019). "The results indicate that only a few RNA modification genes are relevant across multiple cancers; for example, IGF2BP3 demonstrates significant prognostic value in six cancers and has been suggested as a diagnostic and prognostic marker for various cancers, particularly gliomas." (PMID 40867324, 2025). "Regarding the role of IGF2BP3 in the carcinogenicity of circNEIL3, it has been found that circNEIL3 is packaged as an exosome by hnRNPA2B1 and transferred to infiltrate tumor-associated macrophages (TAMs), thus gaining immunosuppressive properties that promote glioma progression." (PMID 38072944, 2023). "Intriguingly, high expression of IGF2BP3 was associated with a poor prognosis not only in hematologic malignances but also in other solid tumors, such as colon cancer, uveal melanoma, mesothelioma, lung adenocarcinoma, glioma, renal papillary cell carcinoma, and renal clear cell carcinoma." (PMID 35217832, 2022). "Finally, circNEIL3 could be packaged into exosomes by hnRNPA2B1 and transmitted to infiltrating glioma-associated macrophages, thereby enabling them to acquire immunosuppressive properties by stabilizing IGF2BP3, which in turn promotes glioma progression." (PMID 35031058, 2022). "In addition, gene chip analysis in glioma cells indicated that IGF2BP3 mediates the association between direct targets at the transcriptome level and processes related to the cell cycle as well as the association between direct targets at the translatome level and apoptosis-related pathways." (PMID 32943100, 2020). "Similarly, another insulin-like growth factor-binding protein encoded by IGF2BP3 (rank 7) may also be an optimal differential marker for the identification of different glioma subtypes." (PMID 30322114, 2018). "Similar to IGF2BP1, IGF2BP3 is a carcinogenic protein that significantly promotes the progression of glioma." (PMID 40469294, 2025).
glioma (continued). "Clinically, the RMS model overcomes the limitations of individual cancer prognostic markers, such as the independent predictive value of IGF2BP3 in glioma." (PMID 40867324, 2025). "IHC analysis revealed that IGF2BP3 expression was barely detectable in normal mouse brain tissue, while it was prominently expressed in xenograft glioma tumors." (PMID 38429265, 2024). "Knockdown studies in glioma cells reveal that IGF2BP3 is integral to cell proliferation, invasion, and migration." (PMID 38474421, 2024). "Compared to other IGF2BPs, IGF2BP3 shows a higher correlation with stemness markers and immune infiltration in gliomas." (PMID 38474421, 2024). "In glioma endothelial cells, IGF2BP3, in combination with METTL3, stabilizes CPEB2, maintaining the blood–tumor barrier and thereby influencing drug delivery." (PMID 38474421, 2024). "In glioma, HNRNPA2B1 can package circNEIL3 into exosomes and transmit them to infiltrating tumor-associated macrophages, stabilizing IGF2BP3 so that macrophages in the TME can acquire immunosuppressive properties, thereby promoting glioma cell proliferation." (PMID 39268079, 2024). "One possible explanation is that, in the contacted co-culture system, glioma cells expressing a high basal level of IGF2BP3 can stimulate a relatively strong NET formation." (PMID 38167409, 2024). "While previous studies have highlighted IGF2BP3’s role in promoting cell proliferation, migration, and invasion in glioma, the specific targets and the intricate mechanisms through which IGF2BP3 regulates cell growth and death remain elusive." (PMID 38429265, 2024). "Using single-sample gene set enrichment analysis (ssGSEA), we found a significant positive correlation between IGF2BP3 expression and infiltrating neutrophils in gliomas, suggesting a possible role of IGF2BP3 in regulating neutrophil function." (PMID 38167409, 2024). "IGF2BP3 was significantly overexpressed in gliomas, correlating with higher glioma grade and poor prognosis in patients." (PMID 38167409, 2024). "Our study offers insights into IGF2BP3’s mechanistic roles and functional implications, unveiling new possibilities for targeted therapeutic strategies in glioma." (PMID 38429265, 2024). "In this study, we demonstrate that, in glioma, upregulation of IGF2BP3 enhances the expression of E3 ubiquitin protein ligase MIB1, promoting FTO degradation via the ubiquitin-proteasome pathway." (PMID 38167409, 2024). "In this study, we demonstrated that IGF2BP3 knockdown is detrimental to cell growth and survival in glioma cells." (PMID 38429265, 2024). "Studies have found that the transcription factor NF‐κB directly binds to the IGF2BP3 promoter region after entering the nucleus to maintain and migrate glioma stem‐like cells." (PMID 38358034, 2024). "The Insulin-like Growth Factor 2 mRNA-Binding Proteins (IGF2BP) family, comprising IGF2BP1, IGF2BP2, and IGF2BP3, plays a crucial role in glioma development and response to treatment." (PMID 38474421, 2024). "The value of a high IGF2BP3 level as an indicator predicting poor prognosis in glioma patients was confirmed by another study." (PMID 38398118, 2024). "This transfer promotes the suppression of the immune response by stabilizing IGF2BP3, thereby facilitating glioma progression." (PMID 38474421, 2024). "To investigate the functional role of IGF2BP3, we knocked down IGF2BP3 in glioma cells, including HS683 (LGG cell line), U87 (GBM cell line), and U251 (GBM cell line)." (PMID 38429265, 2024). "Here the authors report that IGF2BP3 facilitates NETosis and glioma survival as well as resistance to oncolytic herpes simplex virotherapy." (PMID 38167409, 2024). "Remarkably, IGF2BP3-induced NETosis significantly enhanced glioma cell survival in an IGF2BP3-dependent manner, and this effect was abolished in neutrophils from PAD4-/- mice." (PMID 38167409, 2024).
glioma (continued). "Subsequent analysis demonstrated that patients with gliomas exhibiting high IGF2BP3 expression experienced a significantly diminished probability of survival compared to those with low IGF2BP3 expression." (PMID 38398118, 2024). "As we have identified IGF2BP family as the binding proteins of internal m7G and can promote decay of the target transcripts, we asked if IGF2BPs, especially IGF2BP3, are involved in the regulation of m7G methylation in glioma given the correlation with METTL1." (PMID 39198433, 2024). "A similar risk signature (ALKBH5, IGF2BP2, IGF2BP3, HNRNPA2B1, YTHDF1, YTHDF2, RBM15, and WTAP) was shown to be prognostic for glioma patients, and the expression of IGF2BP2 and IGF2BP3 was linked to tumour occurrence, development, and progression." (PMID 36831575, 2023). "The results showed that IGF2BP3 protein expression was significantly higher in glioma compared to normal tissue, especially in GBM." (PMID 36761737, 2023). "This suggests that future studies on glioma should further focus on the relationship between methylation and IGF2BP3 gene expression." (PMID 37298373, 2023). "Conversely, the IGF2BP3 was negatively correlated with cell cycle and DNA damage in Glioma, apoptosis in NSCLC, DNA repair, cell cycle, and DNA damage in RB, angiogenesis in AML, DNA repair, DNA damage, apoptosis, and differentiation in UM." (PMID 36761737, 2023). "We further examined the associations of IGF2BP3 with prognosis (OS, DSS and PFI) in different clinical glioma subgroups." (PMID 36761737, 2023). "In glioma, IGF2BP3 enhances the stability of lncRNA WEE2-AS1 in an mA-dependent manner, attenuating drug sensitivity." (PMID 37298373, 2023). "In glioma cells, upregulation of IGF2BP3 expression promotes tumor proliferation, invasion, migration and angiogenesis, and is also significantly associated with lower survival rates." (PMID 38053093, 2023). "By interacting with miR-654, circHIPK3 increases glioma cell proliferation and invasion, thereby stabilizing IGF2BP3." (PMID 37964279, 2023). "Specifically, the expression level of IGF2BP3 increased significantly with increasing WHO grade gliomas." (PMID 36761737, 2023). "In glioma, exosomal circNEIL3 derived M2 macrophages infiltrated into the TME enabling them to acquire immunosuppressive properties by stabilizing IGF2BP3 and in turn promoting glioma progression." (PMID 37213665, 2023). "Accumulating evidence suggests that EWSR1-induced circNEIL3/IGF2BP3 enhances glioma progression by regulating macrophage polarization and circRNA-0002109 enhances glioma malignant progresses by regulating the miR-129-5P/EMP2 axis." (PMID 37540226, 2023). "We first evaluated the protein levels of IGF2BP3 in a series of clinical specimens, including nine glioma tissues (three specimens each from WHO grade 2,3,4 groups) and three peritumoral normal tissue using immunohistochemistry." (PMID 36761737, 2023). "In this study, two glioma subgroups were identified based on the expression of m6A regulators, and a risk signature (ALKBH5, IGF2BP3, KIAA1429, and YTHDF2) was significantly associated with prognosis, the immune microenvironment and treatment efficacy." (PMID 36831575, 2023). "Further, a recent study revealed that m6A methylation regulators, IGF2BP2 and IGF2BP3, in particular, play essential roles in the malignant progression of glioma." (PMID 36761737, 2023). "CircNEIL3 is packaged into the exosomes by hnRNPA2B1 and is delivered to TAMs from glioma cells, afflicting an immunosuppressive phenotype by stabilizing the IGF2BP3 protein, thereby promoting glioma progression." (PMID 36009578, 2022). "We then stratified glioma samples from the TCGA datasets into high and low expression groups based on the median expression of IGF2BP3 and obtained similar results through differential expression and enrichment analysis." (PMID 35031058, 2022).
glioma (continued). "Especially, preliminary studies demonstrate the IGF2BP3 as a potential negative regulator of glioma tumorigenesis by modulating stemness." (PMID 36686749, 2022). "Investigation of the functional role of IGF2BP3 in glioma stem cells(GSCs) were performed by sphere formation, cytotoxicity, transwell, and wound healing assays." (PMID 36686749, 2022). "For example, insulin-like growth factor 2 binding protein 3 (IGF2BP3) was experimentally shown to bind with circNEIL3 through the region of KH3–4 of in glioma cells." (PMID 36139074, 2022). "CircNEIL3 promotes glioma progression and exosome-mediated macrophage immunosuppressive polarization via stabilizing IGF2BP3." (PMID 35945192, 2022). "Similar to circNEIL3, high IGF2BP3 expression in glioma samples from the TCGA dataset showed similar results, suggesting that circNEIL3 is involved in the recruitment of macrophages." (PMID 35031058, 2022). "Specifically, we demonstrated the role of IGF2BP3 as a potential negative regulator in glioma, which it performs by modulating the TME and stemness." (PMID 36686749, 2022). "Overall, these results indicated that IGF2BP3 can act as the downstream effector of circNEIL3 in macrophages and enable them to acquire immunosuppressive properties, in turn promoting glioma progression." (PMID 35031058, 2022). "Unlike the findings in lung cancer, we first demonstrated HECTD4 as an E3 ubiquitin ligase that can induce ubiquitination of IGF2BP3 in glioma." (PMID 35031058, 2022). "Similar to our observations with circNEIL3, the panel of macrophage-derived immunosuppressive genes was dramatically upregulated in IGF2BP3 high expression gliomas compared with IGF2BP2 low expression gliomas in the TCGA dataset." (PMID 35031058, 2022). "Meanwhile, we observed that circNEIL3 can bind to IGFB2P3 to block the interaction between IGF2BP3 and HECTD4 and induce the upregulation of IGF2BP3 in glioma." (PMID 35031058, 2022). "To further validate the function of IGF2BP3 in the regulation of glioma stemness, we verified the expression of IGF2BP3 in glioma cells (U251 and HS683) and in the peripheral blood of GBM patients." (PMID 36686749, 2022). "Alessandro examined IGF2BP3 expression in a series of 135 patients with high-grade gliomas (grades III and IV)." (PMID 34721530, 2021). "CircHIPK3 serves as a prognostic marker to promote glioma progression by regulating miR-654/IGF2BP3 signaling." (PMID 33858489, 2021). "Molecular mechanism investigations revealed that RMRP exerted its functions by reducing ZNRF3 expression and ZNRF3 mRNA stability via IGF2BP3 in glioma." (PMID 34657141, 2021). "For example, circHIPK3 was upregulated in glioma, which promoted glioma cell proliferation and invasion via the miR-654/IGF2BP3 axis." (PMID 34150336, 2021). "We then analyzed the relationship between IDH status and expression levels of IGF2BP3 in different grades of gliomas." (PMID 34721530, 2021). "Our study highlighted IGF2BP3 as a potential prognostic predictor as well as a therapeutic target for glioma." (PMID 34721530, 2021). "They found IGF2BP3-positive high-grade gliomas showed shorter OS and confirmed the role of IGF2BP3 as a marker of poor outcomes." (PMID 34721530, 2021). "Then we analyzed the OS of patients with glioma, and found that the OS of patients with high IGF2BP3 expression was significantly reduced (p < 0.001), which was consistent with the results of the TCGA." (PMID 34721530, 2021). "Among these RBPs, IGF2BP3 was picked out for further examinations given its noticeably high expression in glioma tissues." (PMID 34657141, 2021). "For instance, IGF2BP3 knockdown hindered glioma cell proliferation and cell cycle progression and inhibited glioma stem-like cell migration." (PMID 34657141, 2021). "IGF2BP3 is a prognostic marker of poor outcome for colorectal cancer, glioma, and papillary renal cell carcinoma." (PMID 32391055, 2020).